ENSG00000274866
Gene: Miscellaneous RNA gene on chromosome 11 (1,997,484 to 1,997,552, forward strand). Ensembl gene ENSG00000274866.
Homologues: Orthologues: mouse Gm56421 (91% identical).